EZH2 (enhancer of zeste 2 polycomb repressive complex 2 subunit)
Diseases named in the same sentence as EZH2 in open-access papers (continued):
Sharing a sentence is not in itself a finding about the gene and the disease.
cancer (continued). "Here we show that DZNep reduces Otx2/c-MYC cancer cells growth ex vivo highlighting a possible therapeutic function of EZH2 inhibition." (PMID 31996670, 2020). "Recent studies also reported that inhibition of enhancer of zeste homolog 2 (EZH2), the catalytic subunit of PRC2, caused synthetic lethality in ARID1A‐mutated cancers." (PMID 32162380, 2020). "Evidence also indicates that the post-translational modifications (PTMs) of EZH2 are crucial for its protein stability, enzymatic activity, and its function in cancer development." (PMID 33308321, 2020). "The inflammatory chemokine (CCL5) contributing to metastasis of cancer cells was downregulated in A549 and A129L transfected with EZH2‐shRNA2# in both mRNA and protein levels." (PMID 31855281, 2020). "When phosphorylation of EZH2 occurs and what effects phosphorylation has on EZH2 are very changeable in different kinds of pathological conditions or different kinds of cancers." (PMID 33308321, 2020). "Through modulating critical gene expression, EZH2 also plays a role in cancer development and progression by promoting cancer cell survival and invasion." (PMID 32850364, 2020). "EZH2 and EZH2 mediated trimethylation of histone H3 lysine 27 (H3K27me3) was previously shown ectopically expressed in carcinoma and mediated proliferation, thereby we sought to clarify the role of EZH2–H3K27me3 in the proliferation of psoriatic keratinocyte." (PMID 33011750, 2020). "EZH2 is highly expressed in a wide range of cancer types, including CRC, and the overexpression of EZH2 is often correlated with advanced cancer stages and poor prognosis." (PMID 30626446, 2019). "EZH2 up-regulation has been found in several cancers, including breast, bladder, prostate, and non-Hodgkin lymphoma." (PMID 30823421, 2019). "Synergistic or re-sensitizing effects between EZH2 inhibitors and traditional cytotoxic anti-cancer drugs have been seen." (PMID 31752930, 2019). "Co-treatment with docetaxel overcame EZH2 inhibitor resistance in PTEN-negative cancer cells in vitro and in mice." (PMID 31410199, 2019). "Among the targets in our chemical probe collection, several have agents currently in clinical trials for cancer (EZH2, EED, DOT1L, PRMT1, and PRMT5) and additional PMT inhibitors are in preclinical studies." (PMID 30604761, 2019). "A striking example that illustrates the dichotomous role of epigenetic regulators in physiology and cancer is enhancer of zeste homologue 2 (EZH2), particularly when examining its function within the central nervous system (CNS)." (PMID 31468686, 2019). "In mouse, overexpression of ENHANCER OF ZESTE HOMOLOG 2 (EZH2) and the consequent high level of H3K27me3 are hallmarks of several cancers, making EZH2 an ideal therapeutic target." (PMID 31619182, 2019). "Our findings suggest that EZH2 repression of FOXO1 can be targeted by EZH2 inhibitor as a monotherapy for PTEN-proficient cancers or in combination with taxane for treatment of cancers with PTEN mutation or deletion." (PMID 31410199, 2019). "Higher activity of Ezh2 has been reported in different cancers such as breast, lung, and prostate, as well as hematological malignancies, and is associated with poor disease prognosis." (PMID 31320814, 2019). "Wolf-Hirschhorn syndrome candidate gene-1 (WHSC1), a histone methyltransferase, has been found to be upregulated and its expression to be correlated with expression of enhancer of zeste homolog 2 (EZH2) in several cancers." (PMID 31092221, 2019). "Our previous studies demonstrated that inhibition of epigenetic modification enzymes EZH2, LSD1, DNMTs, and HDACs caused post-mitotic neuron-like differentiation in different cancer cells." (PMID 31130994, 2019). "In cancer, epigenetic modifications affect the expression of Enhancer of Zester Homolog 2 (EZH2), and silenced disabled homolog 2 interacting protein gene (DAB2IP) (onco-suppressor gene) by Histone H3 tri-methylation in lysine 27 (H3K27me3)." (PMID 31666665, 2019).
cancer (continued). "As an important member of the Polycomb-group (PcG) family, dysregulation of EZH2 via complexation with a range of lncRNAs has been disclosed in some human cancers." (PMID 31534128, 2019). "A number of epigenetic therapies such as SIRT1 inhibitors, HDAC inhibitors and EZH2 inhibitors are currently in clinical trials for many cancer indications, and have shown promise in murine models and good safety profiles in Phase I healthy individuals." (PMID 31380371, 2019). "EZH2 maintains stem-like features in cancer, while cisplatin-based chemotherapy can enrich for stem-like cells leading to chemo-resistance." (PMID 30692641, 2019). "For example, DANCR, which was also up-regulated in young vaccine responders at day 7, as discussed in a previous publication, was found to influence the activity of Enhancer of Zeste Homolog 2 (EZH2) in multiple cancer types." (PMID 31399544, 2019). "RNA expression of TOP2A, PCNA, SOX2, EZH2, ZEB1 genes associated with cell cycle, cancer cell ‘stemness’, and FOXM1‐FOXO activities was similarly affected in both cases." (PMID 30927552, 2019). "EZH2 aberration has been seen in a wide range of cancers, including several categories of B cell and T cell lymphoid malignancies, and it is associated with poor clinical prognosis and outcomes." (PMID 31752930, 2019). "EZH2, which usually overexpressed in serious types of cancer, contributes to tumorigenesis through regulating microRNA expression." (PMID 31171769, 2019). "Overexpression of EZH2 is frequently observed in many cancer types, including prostate, breast, bladder, ovarian, lung, liver, gastric esophageal, pancreatic cancer, melanoma, and osteossarcoma." (PMID 31886200, 2019). "Due to stronger effect of EZH2 knockdown on neuronal differentiation in different cancer cells, we subsequently focused on the role of EZH2 in the regulation of expression of HDAC1, LSD1, or DNMT1, and of β-CAT and SMAD transducers as well." (PMID 31130994, 2019). "EZH2 is overexpressed and mutated frequently in RCC and other types of tumors, contributing to tumorigenic potential of cancer." (PMID 30755832, 2019). "In fact, a previous report demonstrated that EZH2 was overexpressed in many solid cancers, suggesting the positive therapeutic efficacy of EZH2 inhibitors for cancers, including gastric cancer." (PMID 31043675, 2019). "During the last decade, EZH2 has generated much interest as a potential anti-cancer therapeutic strategy." (PMID 31552175, 2019). "According to the existing data, elevated expression of EZH2 has been detected in a wide spectrum of cancers, especially in brain tumors, suggesting its tumorigenic potential." (PMID 31380279, 2019). "PRC2/EZH2 inhibition has emerged as a potential precision therapeutic strategy for genetically defined UTX/KDM6A null cancers that acts by rebalancing the H3K27me3 levels at specific genes." (PMID 31221981, 2019). "Supporting our results, recent reports have questioned the use of EZH2 inhibitors as an efficient cancer therapy." (PMID 31476112, 2019). "MiR-203 is a cancer suppressor that interacts with different genes involved in hepatocarcinogenesis, such as EZH2 and BMI1, SURVIVIN, RASAL2, ADAM9, and MMP2." (PMID 31073374, 2019). "Enhancer of zeste homolog 2 (EZH2), a histone methyltransferase, is highly amplified in human cancers and plays an important role in the development and progression of cancers." (PMID 31395079, 2019). "Another critical target of EZH2 in multiple cancers is the E-cadherin gene, whose downregulation is critical for EMT and metastasis." (PMID 30626446, 2019). "EZH2 is upregulated in many cancers, and the inhibition of PRC2 catalytic activity has emerged as a promising therapeutic approach in cancer." (PMID 31514410, 2019). "Currently, a number of EZH2 inhibitors are tested in phase I/II clinical trials in other cancer entities." (PMID 30898143, 2019).
cancer (continued). "The present model also reconciles some published data on cancer, which indicate that, in several human cancer cells, Kaiso is found in the cytoplasm and Suz12 or EZH2 is overexpressed in the nucleus." (PMID 30940992, 2019). "Enhancer of zeste homolog 2 (EZH2) is one of the most widely studied histone methyltransferases in cancer research." (PMID 31092221, 2019). "Enhancer of zeste homolog 2 (EZH2) is a gene which has been shown to be overexpressed in a variety of cancers and assist in their proliferation." (PMID 30959836, 2019). "EZH2 is a master regulator of chromatin and accumulated evidence suggests that it is involved in aberrant transcriptome in cancer cells." (PMID 31886200, 2019). "Arid1a is part of the SWI/SNF chromatin remodeling complex and has an antagonistic relationship with Ezh2 of the PRC2 complex in cancer development." (PMID 31259687, 2019). "A functional study has reported that EZH2 usually works as an inhibitor of cancer suppressor genes and that lncRNAs can regulate the growth and metastasis of tumor cells by binding to EZH29." (PMID 31371698, 2019). "HOXB13-AS1 is able to contribute to cancer cells proliferation by binding with the enhancer of zeste homolog 2 (EZH2), epigenetically suppressing HOXB13 expression of its neighbor gene." (PMID 31137568, 2019). "This suggested that the main mode of action of EZH2 differed between normal and cancer cells in the adrenal gland." (PMID 31363169, 2019). "Functionally, MALAT1 promotes EZH2 occupancy and increases H3K27 trimethylation level at Polycomb target loci, thereby enhances EZH2-mediated gene repression, cell invasion and migration of cancer cells." (PMID 30788509, 2019). "Here in this study by taking gene overexpressed by more than 1.3 fold as cut-off we gave importance to the biology of cancer to identify the unexplored existing targets of global gene repressor EZH2." (PMID 30760814, 2019). "Single knockdown of HDAC1, HDAC2, HDAC3, LSD1, DNMT1, and EZH2 generated different effects of neuron-like differentiation in cell lines of different cancer types." (PMID 31130994, 2019). "According to the bioinformatics database, EZH2, a critical oncogene that regulates multiple cellular processes in cancers, was a candidate target of miR‐4465." (PMID 31119871, 2019). "Recent studies have revealed a dichotomous role of EZH2 in physiology and in the pathogenesis of cancer." (PMID 31752930, 2019). "A working model summarizes that in cancer cells, EZH2 recruits USP7 and interacts with other proteins, stabilizes these proteins, thereby repressing the expression of neuron-differentiation genes." (PMID 31130994, 2019). "The methyltransferase Ezh2 has pleiotropic effects during development and homeostasis and in pathological conditions such as cancer." (PMID 30890554, 2019). "Given that EZH2 overexpression is a reliable predictor of various cancer progressions, several small molecule inhibitors have been developed for therapeutic treatments and are currently in clinical trials." (PMID 33912356, 2019). "Identifying the regulatory mechanism that underlies EZH2 overexpression in CRC is crucial for further understanding the tumorigenic process and the development of novel approaches for cancer therapy." (PMID 30038060, 2019). "Many studies have proven that EZH2 is upregulated in several types of cancers and has anti-cancer therapeutic potential." (PMID 31092221, 2019). "In the present study, we validated six direct targets of EZH2 that are GPNMB, PMEPA1, CoL5A1, VGLL4, POMT2 and SUMF1 associated with cancer related pathways." (PMID 30760814, 2019). "Treatment of CRC cells with an anti-cancer substance named methyl jasmonate led to apoptosis and inhibited expression of EZH2 while upregulated miR-101-3p expression." (PMID 31864341, 2019). "It was previously demonstrated that restoring TIMP3 function by blocking the expression of its suppressor gene EZH2 (using RNA interference) led to subsequent inhibition of cancer cell migration." (PMID 31921636, 2019).
cancer (continued). "If EZH2 or other PRC2 components are lost in these cells due to mutations, oncogenic insults can induce aberrant cell behaviour more easily and cancer development is favoured." (PMID 31468686, 2019). "For this reason, it is not surprising that reports about the prognostic significance of EZH2 in cancer are highly divergent." (PMID 31317325, 2019). "EZH2 was highly expressed in several human tumors, whose upregulation promoted cell proliferation and amplified in cancer." (PMID 30646895, 2019). "Enhancer of zest homolog 2 (EZH2) is a histone methyltransferase which plays a crucial role in cancer progression by regulation of genes involved in cellular processes such as proliferation, invasion and self-renewal." (PMID 29864144, 2018). "Tazemetostat is now undergoing various phase II clinical trials and the application of this EZH2 inhibitor in different cancers is expected in the coming years." (PMID 28717873, 2018). "In the recent years, the enhancer of Zeste 2 (EZH2) is considered to be a therapeutic target in cancer research." (PMID 29642503, 2018). "The therapeutic approaches have indicated that EZH2 controls diverse phenotypic features of cancer including proliferation, invasiveness, metastasis and resistance to cell death." (PMID 29642503, 2018). "Epigenetic modifiers such as HATs, EZH2, SMRT, and TET1/2 are frequently mutated in human cancer, specifically in leukemia/lymphoma, carcinomas, and sarcomas, all of which are associated with severely altered transcription." (PMID 29728695, 2018). "The expression of EZH2 in cancer is also regulated by post-transcriptional mechanisms through microRNAs." (PMID 29556394, 2018). "EZH2 reportedly promotes cell proliferation, migration and invasion in different in vitro cancer cell models." (PMID 30469511, 2018). "Through modulating critical gene expression, EZH2 promotes cell survival, proliferation, epithelial to mesenchymal, invasion, and drug resistance of cancer cells." (PMID 29556394, 2018). "The increased expression of EZH2 has been shown in several cancers, including metastatic prostate and breast cancer, and is a predictor of a poor clinical outcome." (PMID 30103412, 2018). "Unsurprisingly, numerous studies have highlighted the role of EZH2 in cancer development and progression." (PMID 29556394, 2018). "EZH2 has also been identified as critical to cancer stem cell expansion and maintenance in various malignancies through its action on BMP signalling, AKT/EZH2/STAT3 signaling, Wnt/β-catenin signalling and Notch signalling." (PMID 30555699, 2018). "By screening of library compounds, we identified a novel hybrid epi-drug MC2884, a HAT/EZH2 inhibitor, able to induce bona fide cancer-selective cell death in both solid and hematological cancers in vitro, ex vivo and in vivo xenograft models." (PMID 29876013, 2018). "A pre-clinical study of the HMTi CPI-1205, which targets EZH2, indicated that intratumoral regulatory T cells were reprogrammed, which enhanced the immune response against the cancer cells." (PMID 30558227, 2018). "EZH2 has been considered to be overexpressed in many cancer types and to be transcriptionally regulated by oncogenic signaling to promote cancer cell proliferation and disease progression." (PMID 29556394, 2018). "Further support to the connected action of EZH2 and HMGA proteins derives from studies on other cancers in which EZH2 and HMGA (frequently HMGA2) converge towards the oncogenic achievement." (PMID 29853899, 2018). "In breast (MCF-7, T47-D, and MDA-MB-231) and prostate (LNCaP, DU145, and PC3) cancer cell lines, EZH2 directly repressed RKIP transcription by inducing H3K27 trimethylation on its promoter, leading to increased metastasis." (PMID 34991274, 2018). "The roles of Ezh2 have attracted significant attention due to its critical involvement in tissue growth, homeostasis, and cancer development." (PMID 29408885, 2018).
cancer (continued). "Subsequent high-throughput screening identified novel selective EZH2 inhibitors with potent anti-cancer effect in vitro and in experimental animals." (PMID 28717873, 2018). "Alterations in the expression and activity of polycomb proteins as EZH2 and MLL have been associated with the development of many cancers, including AML, ALL, and multiple myeloma." (PMID 30627525, 2018). "Transcriptomic profiling revealed large-scale transcriptomic alteration by EZH2 inhibition highly enriched for cancer-related pathways." (PMID 29774113, 2018). "Enhancer of zeste homolog 2 (EZH2), the catalytic subunit of PRC2, is commonly mutated or overexpressed in cancer." (PMID 30559935, 2018). "Extensive literature exists about the role of EZH2 as histone methyltransferase and, particularly, about EZH2 involvement in a wide range of malignant tumors due to its function as epigenetic silencer." (PMID 30367633, 2018). "The common findings are that EZH2 levels are deregulated in cancer tissues compared with corresponding normal tissues, and that high EZH2 levels correlate with advanced stages of disease and poor prognosis." (PMID 30761216, 2018). "Enhancer of zeste homolog 2 (EZH2) is a histone methyltransferase that is of great interest in human cancer." (PMID 30555699, 2018). "In a sought to identify the mechanism responsible for the synergistic effect of the combined treatment, our data demonstrated a striking reduction of EZH2, the epigenetic regulator as well as a cancer driver, by the combinative treatment." (PMID 30555330, 2018). "Initially, based on TargetScan (TargetScan Human 7.0) analysis and published literature, we found that EZH2 is a direct target of let-7c in cancer cells and has a highly conserved let-7c binding site in its 3′-UTR." (PMID 29445149, 2018). "Our reported observation that PARP1 and EZH2 interact after DNA damage bear important translational consequences as PARP1 inhibitors are currently used to treat cancer." (PMID 29535829, 2018). "Accumulating evidence strongly suggests that EZH2 expression levels/activity are up-regulated in cancers." (PMID 30341286, 2018). "In cancers with genetic alteration in EZH2, such as various forms of lymphoma, EPZ005687 reduces H3K27 methylation." (PMID 30466474, 2018). "The chromatin modifier EZH2 is a histone methyltransferase that is often over-expressed in many cancers including HCC." (PMID 30035186, 2018). "Evidences have demonstrated that EZH2 is capable of reprogramming the gene program essential for the proliferation, stemness and metastasis of cancer cells." (PMID 30555330, 2018). "NSCLCs and many other tumors exhibit Ezh2 overexpression, which is considered oncogenic and is used as a prognostic factor for outcomes in several human cancers." (PMID 30487290, 2018). "EZH2 is known to be highly expressed in many cancers, and elevated levels of JARID2 have been implicated in several cancers as well." (PMID 30119689, 2018). "Increased Ezh2 expression has been reported in different types of cancers, including colorectal cancer, hepatocellular carcinomas, and lung cancer." (PMID 29335012, 2018). "The second paradoxical role of EZH2 and KDM6B during EMT and cancer aggressiveness is that they are also inactivated or under-expressed in some cancer types and linked to epithelial phenotypes in other cancer cell lines." (PMID 34991274, 2018). "Inhibition of PARP by PARPi attenuates alkylating DNA damage-induced EZH2 downregulation, thereby promotes EZH2-mediated gene silencing and cancer stem cell property compared with PARPi-untreated cells." (PMID 29556394, 2018). "Much like CDKN2A, the EZH2 gene displays a recurring regulation in seven cancer types (BRCA, KIRC, KIRP, LIHC, LUAD, PRAD, THCA)." (PMID 30005633, 2018). "EZH2 widely regulates gene expression affecting several physiological functions, especially cancer progression." (PMID 29556394, 2018).